CRP (C-reactive protein)
Diseases named in the same sentence as CRP in open-access papers (continued):
Sharing a sentence is not in itself a finding about the gene and the disease.
diabetes (continued). "In our analyses, arthritis, diabetes, heart conditions, and serum homocysteine and C-reactive protein concentrations were significant predictors of walking speed." (PMID 23603014, 2013). "This phenomenon can be demonstrated by interaction between diabetes mellitus and CRP, hypertension, dyslipidemia." (PMID 24039853, 2013). "Contrary to Group 1, Group 4 had the lower prevalence of diabetes and level of hs-CRP, as well as higher levels of serum pre-albumin, albumin, creatinine, and nPCR." (PMID 24305468, 2013). "On the other hand, the current study showed that treatment with quercetin reduces the serum level of CRP in both models of diabetes." (PMID 23717483, 2013). "On the other hand, increased plasma levels of CRP, a key marker of inflammation, have been detected in patients with diabetes mellitus." (PMID 23335852, 2013). "Our results, demonstrated that CRP/oxLDL/β2GPI treatment aggravated lipid deposition, increased IMT value in STZ-induced diabetic AS, promoted AS development and the risk of CVD." (PMID 23531147, 2013). "Several studies have shown that subclinical systemic inflammation, as measured by elevated levels of CRP and IL-6, predicts the development of diabetes." (PMID 23690772, 2013). "Several mutual proinflammatory cytokines and adipocytokines also act on the pathogenesis of autonomic neuropathy and diabetes, such as interleukin 6, C-reactive protein, leptin and adiponectin." (PMID 23424665, 2013). "The trend remained significant even after additional adjustment for smoking, alcohol drinking, hypertension, family history of diabetes, lipid profiles and C-reactive protein." (PMID 22427825, 2012). "The oral lipid overload increased CRP and HOMA-IR in IGT subjects suggesting there is an increase in the risk of vascular thrombosis before the diagnosis of diabetes." (PMID 22474520, 2012). "Among participants with data available on CRP levels (13,228 participants), 1761 (136 in people with diabetes) deaths were recorded during follow-up, of which 590 (61 in people with diabetes) were from cardiovascular disease." (PMID 22876293, 2012). "This nationally representative study of US adults assessed the mediating effects of health behaviors, health insurance coverage, health status and CRP on the association between income and all-cause and CVD/diabetes mortality." (PMID 23185488, 2012). "Glomerular filtration rate <45 ml/min/1.73 m2, age ≥ 61 years, cardiovascular disease (CVD), diabetes, C-reactive protein (CRP) ≥5 mg/L, haemoglobin ≤110 g/L, p-albumin ≤ 35 g/L and overweight were associated with impaired HRQoL." (PMID 22710013, 2012). "It has been shown that elevated serum CRP is a risk factor for CHD, and there is a relationship between increased serum levels of CRP with various CHD risk factors, particularly diabetes and hypertension." (PMID 23049543, 2012). "TNF-α, IL-6, MCP-1 and CRP are elevated in obese individuals, and predict diabetes and cardiovascular disease." (PMID 22984471, 2012). "Acute phase reactants produced in the liver, such as C-reactive protein (CRP) and fibrinogen, are also elevated in obese adults and are implicated in the development of cardiovascular, kidney disease and diabetes." (PMID 22682228, 2012). "Poorer dental status was associated with older individuals, women, lower socioeconomic group, not being married, smoking, physical inactivity, less alcohol intake, obesity, poor self-rated health, diabetes, hypertension and high CRP (p<0.001 in all cases)." (PMID 22363491, 2012). "Obesity, age, gender, and diabetes are important factors that influence variation in blood levels of CRP." (PMID 23049543, 2012). "Long-term clinical studies evaluating the effect of periodontal treatment on CRP values are scarce, especially when patients with diabetes are considered." (PMID 22322513, 2012).
diabetes (continued). "Salsalate on the other hand is a very interesting drug in the context of diabetes and has been shown to reduce CRP, FFA, and triglycerides while increasing insulin sensitivity and adiponectin levels." (PMID 23087692, 2012). "Key words:Periodontal disease, periodontitis, diabetes mellitus type 1, periodontal therapy, C reactive protein." (PMID 22322513, 2012). "Ten explanatory variables were included: GFR, age, gender, CVD, diabetes, Hb, log CRP, p-albumin, MAP and BMI." (PMID 22710013, 2012). "Multivariate analysis was carried out with adjustments for BMI, smoking, family history of diabetes, physical activity, CRP, systolic blood pressure, triglycerides, and each haemostatic variable." (PMID 23249721, 2012). "Because of possible confounding effects on CRP levels, subjects with kidney disease, heart disease, liver disease, diabetes mellitus, cancer, obesity, smoking history, and autoimmune disease were excluded from our study." (PMID 23316107, 2012). "The role of inflammation in diabetes is becoming more evident and elevated circulating interleukin (IL)-1β, IL-6, and C-reactive protein (CRP) are predictive of T2DM." (PMID 23087692, 2012). "The additional analysis with sex-specific quartiles for CRP showed increased odds of developing diabetes among those in the third and fourth quartiles compared to the first quartile after adjustment for age, sex, and cohort." (PMID 23130155, 2012). "The factors independently related to Ang-2 were CRP, diabetes, current smoking, male gender, BMI, age, consumption of 3 or more alcoholic drinks per day, LDL-C and HDL-C, accounting for 18 percent of its variance." (PMID 21672190, 2011). "One-way ANOVA, Kruskal-Wallis test, or chi-square test demonstrated that FPG, 2h-OGTT, HOMA-β, HOMA-IR, TG, WC, AC, WHR, hs-CRP, and IgE levels were significantly higher in patients with pre-diabetes or diabetes mellitus than in the normal glucose group (NGG)." (PMID 22194960, 2011). "Confounding variables such as overweight, ASA classification, arterial hypertension, diabetes mellitus, and perioperative antibiotics were recorded to evaluate their influence on the kinetics of CRP values and WBC count postoperatively." (PMID 21657968, 2011). "More than 40% of participants with prediabetes or diabetes only or MetS only have CRP in the upper tertile, whereas more than 60% of participants with MetS plus prediabetes or diabetes have elevated CRP." (PMID 21989115, 2011). "Elevated plasma levels of inflammatory high-sensitivity C-reactive protein (hs-CRP) were seen in two Asian-population–based cohorts of pre-diabetes." (PMID 22194960, 2011). "After adjustments for educational attainment, hypertension, diabetes, smoking, alcohol consumption, BMI, LDL-C, HDL-C, triglycerides and CRP, the association between VEGF and AMI was attenuated and became non-statistically significant." (PMID 21672190, 2011). "Coronary patients with diabetics complications show significantly positive correlation between hs-CRP-ApoB (r=0.056, p<10-3), hs-CRP-fibrinogen (r=0.415, p<10-3) and hs-CRP-TG (r=0.141, p<10-3)." (PMID 23675214, 2011). "These covariates included age, sex, diabetes, hypertension, body mass index, lipid measurements, C-reactive protein, smoking status, physical activity, diet, income, and education level." (PMID 21714927, 2011). "After adjusting for age, gender, BMI, high sensitive CRP and HOMA-IR, both pre-diabetes and type 2 diabetes were still associated with OSA, odds ratios 3.18 (95% CI 1.00, 10.07), p = 0.049 and 4.17 (1.09, 15.88), p = 0.036, respectively." (PMID 21943153, 2011). "Since gender was shown to be related to ln hs-CRP, further analysis was layered by gender and diabetes status." (PMID 20617007, 2010). "Our study showed, however, that adiponectin, apoB, CRP, and ferritin improved the prediction of diabetes consistently in two independent cohorts even after taking BMI, blood glucose and other classic risk factors into account." (PMID 20396381, 2010).
diabetes (continued). "High CRP in Indigenous Australians has been reported in previous studies including our 'Diabetes and Related diseases in Urban Indigenous population in Darwin region' (DRUID) Study." (PMID 21029470, 2010). "CRP was increased in 25/34 (73.5%) obese patients, in particular in 5/7 (71%) with diabetes (mean 1.1 ± 0.53 mg/dl), indicating a low degree of systemic inflammation." (PMID 20920305, 2010). "Chronic low-grade inflammation, as reflected by elevated plasma levels of CRP, is an independent predictor of cardiovascular disease and diabetes." (PMID 20847810, 2010). "The existence of chronic inflammation in diabetes is mainly based on the increased plasma concentrations of C-reactive protein (CRP), fibrinogen, interleukin-6 (IL-6), interleukin-1 (IL-1), and TNFα." (PMID 20634940, 2010). "Epidemiological evidence suggests that CRP is associated with coronary heart disease (CHD); diabetes and the metabolic syndrome." (PMID 21078191, 2010). "Gender showed a strong relationship with ln hs-CRP (P < 0.001), which was moderated by diabetes status." (PMID 20617007, 2010). "The effect of elevated CRP on diabetes defined by the glucose criterion was mediated through obesity, but elevated GGT was an independent risk factor for diabetes in this Chinese population." (PMID 21076541, 2010). "In summary, the effect of elevated CRP on diabetes defined by the glucose criteria was mediated through obesity, but elevated GGT was an independent risk factor for diabetes by the glucose criteria in this Chinese population." (PMID 21076541, 2010). "And we did not consider patients who underwent surgery or those who had any concomitant disease suspected of raising VEGF, IL-6, or CRP (i.e., chronic inflammatory disorders, diabetes mellitus, ischemic heart disease, etc.)." (PMID 20465852, 2010). "Several prospective studies had shown that serum CRP accelerate or increase the development of diabetes, particularly in women." (PMID 21076541, 2010). "By taking a cutoff of 5.6% with the sensitivity of 74.2% and specificity of 65.2%, the OR for newly diagnosed diabetes by the HbA1c criterion remained unsignificant for CRP and GGT in men and women." (PMID 21076541, 2010). "Smoking was independent predictor in young patients <45 years while diabetes and Hs-CRP was the key predictor in older patient groups." (PMID 20508763, 2009). "In recent studies, a correlation between serum resistin and CRP was demonstrated while investigating patients with diabetes, coronary artery disease, or healthy volunteers." (PMID 19545363, 2009). "In a multivariate model including one measure of stroke severity (NIHSS) and pre-existing diabetes, an elevated CRP was independently predicted both by stroke severity and pre-existing diabetes (p = 0.03; p = 0.04)." (PMID 19400931, 2009). "Other inflammatory markers found in diabetes as elevated levels of sCD14, fibrinogen and CRP that shown a significant correlation with PMNLs." (PMID 18570678, 2008). "For example, among the cases 33% had CRP levels exceeding 3 mg/L, 40.1% were current smokers, 55.1% had hyperlipidemia, 62.8% had hypertension and 12.5% had diabetes." (PMID 18518944, 2008). "Studies also showed that haptoglobin and C-reactive protein were increased significantly in both diabetes and glucose intolerance." (PMID 18795103, 2008). "In univariate Cox analyses, older age, obesity, hypoalbuminaemia, elevated CRP, hyperphosphataemia, peripheral and cerebrovascular disease, diabetes, low dialysis adequacy (eKt/V < 1.2), and lower ultrafiltration were associated with higher mortality, whereas preserved LVEF (≥50%) was protective." (PMID 41517606, 2026). "Compared with excluded dentate participants, those retained in the complete-case cohort were more often female, had lower educational attainment, were less likely to smoke and had slightly higher prevalences of hypertension, diabetes and heart disease, while mean CRP concentrations were similar." (PMID 41453287, 2026).
diabetes (continued). "Overall, systemic immunological profiling supports the safety of topical CCL3 therapy in diabetic mice, as treatment did not exacerbate circulating markers, including IgE and CRP which are commonly elevated in diabetes and linked to disease complications." (PMID 41597195, 2026). "Further analysis revealed that gender (male), hypertension, diabetes mellitus, hyperlipidemia, family history, DBP, TG, FBG, UA, NLR, MLR, and CRP/ALB were independent risk factors for the development of CHD, whereas HDL-C demonstrated an independent protective effect against CHD." (PMID 41869521, 2026). "Notably, diabetes mellitus persists as a particularly potent risk factor, often exerting a stronger influence on CAV risk than hs-CRP alone." (PMID 41523716, 2026). "Combined with markers like hs‐CRP or VCAM‐1, ADMA may improve vascular risk stratification in diabetes." (PMID 41567175, 2026). "For primary prevention in diabetes, a practical panel could include HbA1c (glycemic control), an inflammatory marker (hs‐CRP or IL‐6), an endothelial marker (sVCAM‐1 or ADMA), kidney function (albuminuria and/or eGFR), and a lipoprotein measure (Lp(a))." (PMID 41567175, 2026). "Compared to participants without CircS, CircS patients exhibited higher CVAI, TyG, TyG-BMI, METS-IR, AIP, BMI, WC, TC, LDL-C, uric acid, and CRP levels, with a higher proportion of hypertension and diabetes, while eGDR, sleep duration, HDL-C, creatinine, and BUN were lower." (PMID 41601911, 2026). "Additionally, it was established that disease-associated alterations in cortical thickness and white matter integrity were more obvious with obesity and raised baseline CRP levels than with patients of normal weight with diabetes." (PMID 41281014, 2025). "Previous studies found that elevated levels of leptin, hs-CRP, IL-6, and reduced levels of adiponectin are linked to obesity, but not necessarily diabetes." (PMID 39940942, 2025). "Based on the multivariate analysis, sclerostin was an independent predictor of PAD (odds ratio: 1.054 per 1 pmol/L increase, 95% confidence interval: 1.019–1.090, p = 0.002) after adjusting for body mass index, fasting glucose levels, diabetes, smoking, and CRP levels." (PMID 40731833, 2025). "Advanced age, comorbidities (such as diabetes mellitus and chronic kidney disease), and elevated inflammatory and metabolic markers (including neutrophil count, glucose, CRP, and D-dimer), together with procedural factors like prolonged immobilization, were identified as independent risk factors." (PMID 41008724, 2025). "Age, Cholesterol, Lac, TG, FBG, CRP, SOFA, Diabetes, and Hypertension are all risk factors." (PMID 40475963, 2025). "Moreover, a lower level of another parameter, including CRP—the CRP-to-lymphocyte ratio (CLR)—was significantly associated with longer OS in the group of patients with PC and diabetes mellitus or hypertension." (PMID 40361411, 2025). "Most OSA related measurements, along with hypertension and diabetes, exhibit greater severity and incidence rate in parallel with higher CRP blood level, whereas sleep duration, insomnia, daytime sleepiness and cognitive scores show little difference across the three risk groups." (PMID 40437222, 2025). "The strongest predictors identified were the elevated inflammatory markers (CRP, WBC, ESR), radiographic evidence of osteomyelitis, a U-shaped association with triglycerides (both low and high levels), prior amputation, shorter diabetes duration, higher LDL-C, lower BMI, and reduced eGFR." (PMID 41374452, 2025). "The 2025 ADA guidelines have designated non-HDL-C as a secondary target and recommended CRP monitoring to optimise diabetes risk assessment." (PMID 41357322, 2025). "Our results support this concept by showing a stronger interaction between vitamin D deficiency and CRP on incident diabetes in pre-frail or frail older adults as compared to the non-frail." (PMID 39662157, 2025).
diabetes (continued). "The IPW‐adjusted models controlled for age, gender, PSI score, hypertension, diabetes, chronic kidney disease, coronary heart disease, congestive heart failure, CRP, D‐dimer, NLR, LDH, glucocorticoid treatment, and antiviral therapy, effectively balancing measured confounders between groups." (PMID 40665508, 2025). "Multivariate regression of C-reactive protein–triglyceride–glucose index with diabetes." (PMID 40988175, 2025). "Although we have shown that several variables – including age, CRP at admission, alcohol consumption, hypertension, diabetes mellitus and prior antibiotic exposure – were significantly associated with the outcome in univariate analyses, only age remained associated in the multivariate model." (PMID 41438567, 2025). "However, they exhibited higher levels of TFR, creatinine, blood urea nitrogen, urine albumin creatine ratio, hypersensitive C-reactive protein, and phosphorus, and a higher prevalence of diabetes and hypertension." (PMID 40740730, 2025). "CRP was demonstrated as a predictor of inflammation and incident diabetes." (PMID 39355932, 2025). "Other subgroups—BMI, diabetes, alcohol use, vitamin D deficiency, reduced eGFR, elevated CRP, and age—did not demonstrate statistically significant associations with RA development." (PMID 40722700, 2025). "Univariate analysis showed that sex, age, race, education level, marital status, family income, smoking status, alcohol consumption, physical activity, hypertension, diabetes, CHD, stroke, migraine, hemoglobin level, and C-reactive protein level were associated with symptomatic dizziness." (PMID 40264084, 2025). "CRP is not only a marker of systemic inflammation but also a predictor of diabetes onset." (PMID 41459237, 2025). "Understanding the interplay between adiponectin, leptin, CRP, and IL-6 in this unique demographic may yield important insights into the pathogenesis of lean diabetes." (PMID 41523554, 2025). "Further, one-sample Mendelian randomization analysis did not support a causal association of CRP on neither sleep, diabetes, nor hypertension." (PMID 40437222, 2025). "There is increasing evidence linking CRP, as not just an inflammatory biomarker but also as a risk factor associated with ageing-related diseases like hypertension, diabetes mellitus, cardiovascular diseases, and kidney diseases." (PMID 40362763, 2025). "The following variables were included in the FI: muscle strength, average time spent outdoor, gait speed, numbers of steps taken, balance, p-CRP, p-creatinine, mobility/activity level, diabetes, cancer/severe disease, diseases affecting balance, polypharmacy, and self-estimated risk of falling." (PMID 41364151, 2025). "We examined whether the CRP–DR relationship varied by age, sex, BMI, diabetes duration, treatment modality, or glycemic control, as prior studies have suggested such effects." (PMID 41159344, 2025). "More and more clinical evidence link inflammation, obesity, insulin resistance, and cardiovascular disease, and some inflammatory indicators such as C-reactive protein (CRP) are often used to predict whether diabetes patients have cardiovascular disease." (PMID 40362436, 2025). "Likewise, CRP, an acute-phase reactant, has been connected to the onset of diabetes and cardiovascular problems and increases in response to inflammatory stimuli." (PMID 40407432, 2025). "However, the CVC group demonstrated significantly higher age, prevalence of diabetic nephropathy, comorbid diabetes, Hs-CRP, fasting blood glucose, serum phosphorus, iPTH, and VFA compared to the non-CVC group." (PMID 40276255, 2025). "Relative to patients without a furosemide prescription, patients with a furosemide prescription were older and had a lower eGFR, greater frequencies of previous CV disease, diabetes and acute kidney injury, a higher CRP concentration, a lower hematocrit, and more drug prescriptions." (PMID 40677309, 2025).